NTS (neurotensin)
Description:
Neurotensin may play an endocrine or paracrine role in the regulation of fat metabolism. It causes contraction of smooth muscle.
Synonyms: NN; NT; NMN-125; NT/N; NTS1
Tractability: Small molecule: a structure with a bound ligand is known. Antibody: its Gene Ontology location is reachable by antibodies, with high confidence; UniProt places it where antibodies can reach, with medium confidence; UniProt predicts a signal peptide or a membrane-spanning region.
Gene: Protein-coding gene on chromosome 12 (85,874,162 to 85,882,992, forward strand). Ensembl gene ENSG00000133636.
Subcellular location: Secreted; Cytoplasmic vesicle, secretory vesicle
Subcellular location (Human Protein Atlas): Vesicles; Predicted to be secreted
Pathways (Reactome):
Signal Transduction: G alpha (q) signalling events; Peptide ligand-binding receptors
Gene Ontology:
Molecular function: neuropeptide receptor binding; protein binding; receptor ligand activity; neuropeptide hormone activity
Biological process: negative regulation of gene expression; neuropeptide signaling pathway; positive regulation of gene expression; positive regulation of phosphatidylinositol 3-kinase/protein kinase B signal transduction; signal transduction
Cellular component: axon terminus; extracellular region; transport vesicle
Genetic constraint (gnomAD): Loss-of-function variants: 3 observed, 3.41 expected, observed/expected ratio (o/e) 0.88, 90% interval 0.39 to 1.81. That is too few expected variants to judge how well the gene tolerates losing a copy. Missense variants: 80 observed, 78.34 expected, observed/expected ratio (o/e) 1.02, 90% interval 0.85 to 1.23. Synonymous variants: 29 observed, 26.34 expected, observed/expected ratio (o/e) 1.1, 90% interval 0.82 to 1.5.
Homologues: Orthologues: chimpanzee NTS (99% identical), macaque NTS (96% identical), dog NTS (90% identical), pig NTS (90% identical), rabbit NTS (89% identical), guinea pig NTS (84% identical), mouse Nts (81% identical), rat Nts (77% identical), tropical clawed frog nts (61% identical), zebrafish nts (29% identical).
Diseases named in the same sentence as NTS in open-access papers:
NTS is named in the same sentence as 95 diseases in open-access papers, as found by Europe PMC text mining. Sharing a sentence is not in itself a finding about the gene and the disease. The quoted sentences say what the papers report.
Obesity (24 papers, 2013 to 2025). Accumulation of substantial excess body fat. "In contradiction, neurotensin-deficient mice are reported to be protected against obesity because of neurotensin-induced decreased intestinal fat absorption." (PMID 36316682, 2022). "The aim of the present study was to examine potential associations between neurotensin and xenin in plasma with psychometrically assessed perceived stress, anxiety, depressiveness and eating disorder symptoms in patients with obesity." (PMID 33664656, 2021). "The aim of the present study was to examine associations of neurotensin and xenin with these psychological characteristics under conditions of obesity." (PMID 33664656, 2021). "Importantly, NTS deficiency extended the lifespan compared with WT littermates under both normal conditions and conditions of obesity." (PMID 40451927, 2025). "Neurotensin and xenin seem to be associated with psychopathology under conditions of obesity." (PMID 33664656, 2021). "Furthermore, neurotensin deficient mice were resistant to high-fat diet-induced obesity, and neurotensin decreases AMP-activated protein kinase activity via sortilin." (PMID 28728579, 2017). "Thus, targeting neuropeptides such as neurotensin, substance p and oxytocin might be a beneficial strategy to address cognitive deficits associated under obesity conditions." (PMID 40077655, 2025). "Enhancing neurotensin signalling via overexpression normalized aspects of diet-induced obesity, including weight gain and hedonic feeding." (PMID 40140571, 2025). "Research on neurotensin suggests it plays a role in both obesity and cognitive function, often intersecting with neuroinflammatory pathways that can contribute to cognitive deficits." (PMID 40077655, 2025). "Here, utilizing Drosophila and mouse models in vivo, as well as mouse and human small intestinal epithelial organoids or monolayers ex vivo, we determine the targets of neurotensin and AMPK associated with obesity and aging." (PMID 40451927, 2025). "Few studies have examined the neurotensin level in humans with obesity and the effect of neurotensin on appetite." (PMID 35328759, 2022). "Neurotensin is involved in fatty acid and glucose metabolism and promotes the development of obesity and diabetes." (PMID 35345492, 2022). "Antidiabetic properties of xenin and dysregulations of neurotensin and pro-neurotensin in obesity and high-fat diet are current areas of interest." (PMID 33664656, 2021). "Due to their physiological effects, both neurotensin and xenin have been examined in the context of obesity and in relation to somatic sequelae of the disease." (PMID 33664656, 2021). "Based on previous literature, increased xenin levels following treatment with PPI’s as well as decreased plasma concentrations of neurotensin in women with fatty liver disease and obesity were described." (PMID 33664656, 2021). "In rodents, neurotensin contributes to high fat diet induced obesity by facilitation of intestinal fat absorption." (PMID 32825823, 2020). "Obesity in girls leads to decreased levels of neurotensin relative to eutrophic girls (p = 0.0035), while boys with obesity showed lower levels of MCH (p = 0.0002) and higher NPY content (p = 0.06), as compared to eutrophic boys." (PMID 33644105, 2020). "A recent study showed that mice null for the leptin receptor (LepRb) specifically in neurotensin neurons showed early-onset obesity, modestly increased feeding, and decreased locomotor activity." (PMID 23620827, 2013). "Whether targeting neurotensin signaling or lymphangiogenesis has translatable potential in the epidemic of obesity thus remains to be seen." (PMID 36776563, 2023). "Also, neurotensin knock-out mice are less likely to develop diet-induced obesity, insulin resistance and hepatic steatosis." (PMID 35345492, 2022). "Through the activation of protein CERK, it could stimulate the neurotensin signal to produce excessive fatty acid, resulting in obesity." (PMID 35164166, 2022).
Obesity (continued). "Taken together, we observed positive correlations of neurotensin and xenin with stress, anxiety, depressiveness and eating disorder symptoms in obese women, whereas, associations were absent in male patients with obesity indicating a sex-specific association." (PMID 33664656, 2021). "Orexigenic signaling through increased HPA axis hormones is a further stimulus for obesity and might counteract the anorexigenic effect of neurotensin in CNS." (PMID 33664656, 2021). "Alterations of circulating levels of neurotensin and xenin may be involved in the emergence and maintenance of obesity." (PMID 33664656, 2021). "One molecule related to the pathophysiology of obesity is neurotensin (NT)." (PMID 34200577, 2021). "Brain transcriptome analyses in obese mice identified several obesity-related pathways (e.g. leptin, somatostatin, and nemo-like kinase signaling), as well as genes involved in feeding and appetite (e.g. Pmch, Neurotensin) and in metabolism (e.g. Bmp4, Bmp7, Ptger1, Cox7a1)." (PMID 25629159, 2015). "Moreover, anorexigenic effects of both peptides have been examined, because in animal models of obesity, decreased central concentrations of neurotensin have been detected together with reduced food intake after intracerebroventricular (icv) administration of xenin and neurotensin in rodents." (PMID 33664656, 2021). "In addition, DIO by HFD exposure was recently shown to depend on neurotensin, a neuropeptide with significant dopaminergic interactions, and longitudinal studies in humans have shown that pro-neurotensin plasma level is a reliable predictor for the eventual development of obesity." (PMID 28261067, 2017). "ANOVA revealed that neuropeptide content is markedly altered in obesity, with changes in the expression of α-MSH (α-Melanocyte-stimulating hormone, p = 0.0397), neurotensin (p = 0.0018), and melanin-concentrating hormone (MCH, p = 0.0003)." (PMID 33644105, 2020). "In addition, one of sortilin’s most well-studied ligands, neurotensin, has been shown to play a role in HFD-induced obesity by increasing fat absorption in the intestine." (PMID 35724703, 2022). "Neurotensin knock-out mice (i.e. lacking neurotensin) displayed reduced intestinal fat absorption and abdominal fat accumulation and hence they were substantially protected against diet-induced obesity, insulin resistance and liver steatosis." (PMID 31541150, 2019).
prostate carcinoma (14 papers, 2004 to 2026). A carcinoma that arises from epithelial cells of the prostate gland. "NTS encodes a common precursor of neuropeptide M and neurotensin, and it plays an important role in the central nervous system; it has an important role in tumors, enhancing the progression of pancreatic cancer, prostate cancer, lung cancer, breast cancer, and colon cancer." (PMID 33169793, 2020). "Neurotensin receptor 1 (NTSR1) can combine with neurotensin (NTS) to form a complex to promote tumor progression in solid tumors such as prostate cancer, colorectal cancer, and pancreatic cancer." (PMID 35251577, 2022). "Alternative pathways for the proliferation of prostate cancer cells have been identified, such as the neurotensin/neurotensin receptors axis." (PMID 30959962, 2019). "Preliminary data in the literature incriminate neurotensin and its receptors in prostate cancer with neuroendocrine differentiation." (PMID 30959962, 2019). "Since neurotensin (NT) receptors of subtype-1 (NTS1) are expressed by different types of malignant tumors, such as pancreatic adenocarcinoma, colorectal and prostate carcinoma, they represent an interesting target for tumor imaging by positron emission tomography (PET) and endoradiotherapy." (PMID 36056076, 2022). "Neurotensin has been showed to mediate neuroendocrine differentiation of prostate cancer." (PMID 30959962, 2019). "However, accumulating evidence support the involvement of lysophosphatidic acids, neurotransmitters, and neuropeptides such as bombesin and neurotensin through GPCR signaling in the initiation or progression of prostate cancer." (PMID 15548330, 2004). "Interestingly, androgen deprivation induces acute neurotensin production, suggesting the involvement of neurotensin and its receptors in androgen-independent prostate cancer and/or neuroendocrine differentiation of prostate cancer." (PMID 30959962, 2019). "Neurotensin is indeed able to stimulate prostate cancer cell growth, while the selective neurotensin antagonist (SR48692) decreases prostate cancer cell growth." (PMID 30959962, 2019). "Neurotensin (NT) and neurotensin-like peptide neuromedin N (NMN) are derived from the same polypeptide precursor, neurotensin receptors (NTRS1, NTRS2 and NTRS3) being overexpressed by lung, breast cancer, colon or prostate cancer." (PMID 32722221, 2020).
breast carcinoma (13 papers, 2009 to 2025). "Besides this, ID4, SEMA3F, FOXD, KCNK5, WNK4 and ECM1 associate with chemoresistance origin and SOX5, ITM2A, SNCG, EPHA4, NTS, FGFR2 and ENPEP associate moreover with breast cancer tumorigenesis." (PMID 37239828, 2023). "One molecule of this kind is the neurotensin (NT) for which it has been previously demonstrated to have the potential to target tumours such as: pancreatic cancer, colorectal cancer, lung cancer, prostate cancer or breast cancer." (PMID 33917046, 2021). "Furthermore, there is evidence indicating that blocking the sortilin-neurotensin or sortilin-progranulin interactions might be of interest for the treatment of neuropathic pain and certain forms of breast cancer, respectively." (PMID 39185427, 2024). "Amongst the factors contributing to tumor aggressiveness, neurotensin (NTS) and its cognate high-affinity receptor (NTSR1) have been shown to contribute to breast cancer progression." (PMID 25249538, 2014). "Neurotensin (NTS) and its high affinity receptor (NTSR1) are up regulated in 20% of breast cancers, and NTSR1 overexpression was shown to predict a poor prognosis for 5 year overall survival in invasive breast carcinomas." (PMID 25249538, 2014). "For example, a recent report showed that neurotensin (NTS) and its high affinity receptor (NTSR1) enhances EGFR, HER2, and HER3 activation, but lapatinib could reduce the tumour growth of breast cancer cells overexpressing NTS and NTSR1." (PMID 25691057, 2015).
schizophrenia (13 papers, 2011 to 2024). A major psychotic disorder characterized by abnormalities in the perception or expression of reality. "Neurotensin has been associated with immune and neuroendocrine modulation of enteric function, antinociception, and reward‐related behavior, especially in schizophrenia." (PMID 36414415, 2023). "Neurotensin has been reported to be associated with schizophrenia and memory consolidation, which may also be mediated by high sensitivity." (PMID 21765900, 2011). "Neurotensin's neuroprotective and psychotropic effects have been studied in the context of psychiatric disorders such as schizophrenia and depression." (PMID 39347144, 2024). "Past researches revealed the broad involvement of NT in the nerve systems through neurotensin and dopamine receptors to play a role in numerous brain conditions including Huntington's diseases and schizophrenia." (PMID 33629528, 2021). "In addition, a preclinical study reported increased neurotensin and oxytocin in genetic and/or environmental schizophrenia‐like mice using multiplex immunoassay." (PMID 36414415, 2023). "Several neuropeptides were identified from schizophrenia patient-derived neurons, including chromogranin B (CHGB), neurotensin, and natriuretic peptide." (PMID 38302561, 2024). "For example, TH was related to essential hypertension; DRD2 to childhood temperament, extraversion, and antisocial behavior; and neurotensin genes (NLN, NTSR1, NTRS2) to schizophrenia and memory consolidation." (PMID 26308205, 2015). "Decreased CSF neurotensin concentration has been found in patients with schizophrenia, and improvements in overall psychopathology, including positive and negative symptoms, were correlated with increases in CSF neurotensin concentrations during treatment." (PMID 37275985, 2023). "Our study is consistent with previous research and we find decreased neurotensin in first episode, never treated schizophrenia patients." (PMID 37275985, 2023). "Plasma α‐MSH, β‐endorphin, neurotensin, oxytocin, and substance P levels were not significantly different between patients with schizophrenia, BD, or MDD and healthy controls." (PMID 36414415, 2023). "Psychiatric symptoms or cognitive functions were not correlated with plasma α‐MSH, β‐endorphin, neurotensin, oxytocin, and substance P levels in patients with schizophrenia, BD, or MDD, or healthy controls." (PMID 36414415, 2023). "Plasma α‐MSH, β‐endorphin, neurotensin, oxytocin, and substance P levels were not significantly correlated with psychiatric symptom scores in patients with schizophrenia, BD, or MDD and cognitive function scores in patients or healthy controls." (PMID 36414415, 2023). "Plasma α‐MSH, β‐endorphin, neurotensin, oxytocin, and substance P levels were not different between patients with schizophrenia, BD, or MDD and healthy controls." (PMID 36414415, 2023). "Furthermore, to the best of our knowledge, this study is the first to show that plasma α‐MSH and neurotensin levels are not altered in patients with schizophrenia, BD, or MDD." (PMID 36414415, 2023).
colon carcinoma (10 papers, 2011 to 2025). "The aim of this study was the investigation of neurotensin as a potential agent used in diagnosis and therapy of colon cancer when coupled with 68Ga and 177Lu, respectively." (PMID 33917046, 2021). "The neurotensin is a tridecapeptide involved in the proliferation of colon cancer, the overexpression of neurotensin receptors occurring at an early stage development of many tumours." (PMID 33917046, 2021). "In both mice with colon tumours and those with prostate tumours, the excretion of neurotensin is fast, after 30 min p.i. about 25% ID/g being found in the kidneys and 7–9% ID/g in the bloodstream." (PMID 32722221, 2020). "Numerous cancer cells, including colonic cancer cells, express the receptor family of neurotensin (NT), and particularly Sortilin/NTSR3." (PMID 27834811, 2016). "In the present study, we have found that neurotensin-induced signalling in colon carcinoma cells involves both EGFR-dependent and -independent pathways." (PMID 21961726, 2011). "Neurotensin has been found to stimulate proliferation of certain colon carcinoma cell lines." (PMID 21961726, 2011). "Neurotensin has been found to promote colon carcinogenesis in rats and mice, and proliferation of human colon carcinoma cell lines, but the mechanisms involved are not clear." (PMID 21961726, 2011).
Anxiety (9 papers, 2021 to 2024). Intense feelings of nervousness, tension, or panic often arise in response to interpersonal stresses. "The aim of the present study was to investigate potential associations between plasma levels of neurotensin and xenin and perceived stress, anxiety, depressiveness, and eating disorder symptoms in obese inpatients." (PMID 33664656, 2021). "Some of the well-researched neuropeptides in plasma are oxytocin (OXT), alpha-melanocyte-stimulating hormone (alpha-MSH), beta-endorphin, neurotensin, and substance P. Each of these molecules has been implicated in the regulation of anxiety and depressive disorders." (PMID 39347144, 2024). "A recent study noted that only women showed a positive correlation between neurotensin and perceived stress, anxiety, and depression, aligning with similar findings in animal models." (PMID 39347144, 2024). "EA effectively mitigates both CIP and anxiety by activating parvalbumin neurons in the anterior cingulate cortex, inducing an increase in neurotensin/neurotensin receptor expression, and inhibiting protein kinase Mzeta activity." (PMID 37948105, 2023). "Neurotensin (NT), a 13-amino acid neuropeptide, is present in the bed nucleus of the stria terminalis, which is a structure supposed to be involved in anxiety." (PMID 36004833, 2022). "In a study on patients with acne vulgaris and their quality of life, anxiety, and depression, neurotensin levels were significantly higher in the study group compared to controls." (PMID 36004833, 2022). "Neurotensin and xenin plasma levels of female obese patients are positively correlated with perceived stress, anxiety, depressiveness, and eating disorder symptoms." (PMID 33664656, 2021). "In addition to co-expressing GABA, CRF-expressing neurons also co-express SOM, neurotensin, and dynorphin which have been shown to support distinct roles in anxiety and fear." (PMID 38951506, 2024). "In experiments, neurotensin has been found to increase the transmission in the bed nucleus of the stria terminalis together with corticotropin-releasing factor, whereas a blockade of NT receptors prevented stress-related anxiety-like behaviors." (PMID 36004833, 2022). "Indeed, a population of fear-off neurons expressing NTR2 has been identified in BLA for anxiety regulation, and neurotensin and NTR2 were shown to directly modulate pain resulting from inflammatory stimuli." (PMID 36309729, 2022). "Sex-specific regulation of neurotensin and xenin was found for perceived stress and anxiety." (PMID 33664656, 2021). "This may indicate that higher neurotensin levels contribute to the development and/or maintenance of perceived stress and anxiety." (PMID 33664656, 2021).